KLRG1 (killer cell lectin like receptor G1)
Diseases named in the same sentence as KLRG1 in open-access papers (continued):
Sharing a sentence is not in itself a finding about the gene and the disease.
infection (continued). "Decreased KLRG1 expression on CMV-specific CD-8 TEM following low titer infections further supports this hypothesis." (PMID 27870919, 2016). "Both IFNγ expression in CD4+ and CD8+ T cells as well as Granzyme B expression in CD8+ T cells peaked on day seven post infection which was consistent with the expression of CD11a and KLRG1 on CD8+ T cells, demonstrating that these cells were antigen-experienced effector cells." (PMID 27875529, 2016). "Accordingly, memory cells generated in the context of an acutely resolved infection tend to be less terminally differentiated than T cells associated with persistent infection, and usually express higher levels of CD127 and lower levels of KLRG-1." (PMID 25679375, 2015). "At different days post infection, splenocytes were isolated and stained for KLRG1 and CD127." (PMID 25255454, 2014). "Whilst it is well established that WSX-1 signalling limits IFN-γ production by T cells during infection and inflammation, our study is the first to identify that it does so specifically by preventing the generation of terminally differentiated KLRG-1+ Th1 cells." (PMID 23593003, 2013). "The increase in the fraction of KLRG1+ cells in virus infected mice has been described in several models of infection, and in human CMV specific CD8 T-cells and was shown to remain elevated only in cells responding to persistent viruses, but not to CD8 cells reacting against acute viruses." (PMID 22916012, 2012). "For instance, the KLRG1 ligands, E- and N-cadherin, are expressed in SMG and could potentially inhibit KLRG1+ NK cells during infection." (PMID 21249177, 2011). "Thus, considering ANDV a self-limiting transient infection in man, a CD127+KLRG1− phenotype would have been expected years after the infection." (PMID 20174562, 2010). "We could confirm that NK cells are indeed required to generate KLRG1+ cells upon infection." (PMID 37828009, 2023). "Thus, KLRG1+ iILC2s may be transient ILC progenitors recruited by infection and inflammation into the lung and intestine, where they then develop into nILC2-like cells and ILC3-like cells." (PMID 37696896, 2023). "Although KLRG1+ CTLs can produce large quantities of lytic molecules and proinflammatory cytokines, intranasal infection with LM-OVA does not cause lethal pathology in the lungs, irrespective of whether the TGFβ receptor is present." (PMID 37426662, 2023). "Analysis of Tet2-deficient (Tet2fl/flCd4-cre) CD8 T cells responding to infection with lymphocytic choriomeningitis virus (LCMV) showed increased LCMV gp33-specific memory precursor cells (KLRG1− CD127+) and decreased short-lived effector cells (KLRG1+ CD127−) on day 8 post-infection." (PMID 30809228, 2019). "Further investigations using an experimental VL model caused by infection of C57BL/6 mice with L. donovani revealed that this negative effect was prominent in the liver, dependent on parasite burden and associated with an accumulation of Th1 cells expressing high levels of KLRG-1." (PMID 26872334, 2016). "Data presented in this study also showed a greater ratio of Th1 to Tr1 cells in control mice with low-dose infection, compared to the same group with a high dose infection, and this may contribute to a more activated status that results in a greater proportion of KLRG1+ cells." (PMID 26872334, 2016). "TKS infection under permissive conditions prompted infiltration of activated T cells (CD11ahigh, CD69+, KLRG1+ and PD-1+), along with the recruitment of effector and resident memory T cells." (PMID 39794471, 2025). "By contrast, in IAV‐only infection, a higher proportion of tetramer+CD8+ T cells had CD38+PD‐1+, CD25+CD38+PD‐1+ and KLRG1+ phenotypes." (PMID 39971320, 2025). "At 60 days post‐infection, these mice also showed increased frequencies of CD4+ T cells with activation (CD25+, CD69+ CD25+) and effector memory (KLRG1+) markers in the lungs." (PMID 39039808, 2024).
infection (continued). "KLRG1+ CD8 T cells peaked between 12- and 16-days post-infection, depending on the site of collection, while KLRG1+ NK cells peaked between 8- and 12-days post-infection." (PMID 39150988, 2024). "KLRG1+ CD4 T cells peaked 8 days post-infection in spleen, 24 days post-infection in the SG, and 32 days post-infection in blood." (PMID 39150988, 2024). "Blockade of KLRG1 enhances AKT signaling, reduces lung burden, and prolongs survival time after infection; thus, KLRG1 is a potential target for antituberculosis immunotherapy." (PMID 38898461, 2024). "On the basis of cell transfers and fate-mapping experiments, expression of Klrg1 and CD127 defined two stable aaMAIT populations, despite infection and increases in population size." (PMID 37231163, 2023). "Transient blockade of IL‐27 elicits high levels of unique CD127+ and KLRG1+ memory CD4+ T cells, elevates antibody production, and enhances protective immunity against secondary infection." (PMID 37855243, 2023). "On day 28 of infection, CD127+KLRG1− and CD127−KLRG1+ PbT‐II cells were dominant and reached 39.0 ± 1.4% and 39.9 ± 6.5%, respectively." (PMID 37855243, 2023). "As observed during infection the levels of the differentiation markers CX3CR1 and KLRG1 were reduced and the expression of CTLA-4 increased in T cells from immunized Vhl cKO mice." (PMID 36064840, 2022). "Compared to DGKζ KO mice, there was only a modest increase in the fraction of KLRG1+ cells, whereby an increase was only seen in GP33-specific CD8+ T cells in ERKSEM mice at Day 7 post infection." (PMID 36846018, 2022). "CD127+ KLRG1– cells remained the dominant population until > 40 days post-infection, with small fractions of cells being CD127– KLRG1– CD127+ KLRG1+ or CD127– KLRG1+." (PMID 35844563, 2022). "To generate large populations of KLRG1+ CTLs, we transferred OTI-S4KO and OTI-S4Ctrl cells to B6 mice before infection with LM-OVA and analyzed donor cells in the spleen at 8 dpi using qPCR." (PMID 35942952, 2022). "Several groups used reporter mice to monitor changes CX3CR1 expression during infection with different pathogens and found that terminally differentiated TEFF cells expressed KLRG1 and CX3CR1 at high levels." (PMID 35942952, 2022). "Heatmaps show percentages of donor cells that expressed KLRG1, CD103, CD62L, and CD127 on different day post infection." (PMID 35942952, 2022). "Cytosplore analysis of the GP33-specific CD8+ T cells using the cell surface markers CD44, KLRG1, and CD62L revealed substantial differences in the phenotype of the GP33-specific CD8+ T cells between the three different infections." (PMID 33458613, 2021). "In accordance with the FDS data, we observed a substantially lower proportion of cytokine-expressing KLRG1+ CD4 T cells after MPT70 stimulation compared to ESAT-6, and this difference was sustained throughout the infection." (PMID 33879592, 2021). "Upon MCMV-GP33 infection, two TRM cell clusters expressing CD38, CD11a, CD11c, CXCR6, and Sca-1, typified by divergent KLRG1 expression, connected uniquely to the liver." (PMID 33458613, 2021). "On day 60 post‐infection, OT‐I cells within the brain were primarily CD69+CD103−KLRG‐1− and CD62L−, whereas OT‐I cells within the lung were CD69–CD103–KLRG‐1+ and CD62L− and OT‐I cells within the spleen were predominantly CD69–CD103−KLRG‐1− and CD62L+." (PMID 34407221, 2021). "To this end, we isolated and transferred CD127+KLRG1− and CD127−KLRG1+ WT and KO OT-I T cells at 7 days post infection with Lm-N4 into naive secondary host mice." (PMID 32726622, 2020). "After infection, those cells upregulated the expression of CD11a, CD44 and KLRG-1 and downregulated the expression of CD62L when compared to naïve CD8+ T cells." (PMID 32574175, 2020). "Upon infection, M. tuberculosis-specific CD4 T cells expressing KLRG1 exhibited a heightened capacity to secrete IFN-γ." (PMID 33193338, 2020).
infection (continued). "Our results are slightly at odds with a previous publication that demonstrated that KLRG1+PD‐1+ ILC2 produce more Th2 cytokines following both IN delivery of IL‐33 and during infection with the worm Nippostrongylus brasiliensis." (PMID 31742928, 2020). "We quantified the expression of KLRG1 and CD127 in each subpopulation at days 6, 8, and 35 post-infection." (PMID 33343572, 2020). "While several NK receptors remain unchanged at day 8 post infection (p.i.), NK cells upregulated CD44, KLRG1 and CD11b suggesting activation state." (PMID 33370392, 2020). "In contrast, on day 7 post-infection, a variety of different populations of effector/memory CD8+ T cells were detected in the skin (based on expression of CD127 and KLRG1) and nearly all of the cells had proliferated." (PMID 30875408, 2019). "Eight days post-infection, short-lived terminal effector (TE) P14 T cells (CD45.1+ CD8+ Klrg1+ CD127−) and memory precursor (MP) P14 T cells (CD45.1+ CD8+ Klrg1− CD127+) were isolated from spleens by FACS." (PMID 30643116, 2019). "We found that KLRG1−/CD69+ tissue-resident memory T cells (Trm) in the liver of naïve mice and 7 weeks after infection with Lm express high levels of ARTC2.2 and P2X7." (PMID 30038627, 2018). "In our murine model of memory formation, the expression of KLRG1 was significantly upregulated on CD4 (p = 0.0126) and CD8 (p < 0.0001) T cells in mice that received all three infections compared with mock-infected mice." (PMID 29963060, 2018). "Similar to the spleen, peripheral organs such as the skin and small intestine contain KLRG1+ and KLRG1− fractions within the virus-specific effector CD8 T cell population after infection." (PMID 30131803, 2018). "Absolute numbers of KLRG1+ cNK cells increased in spleen after cps1-1 and ME49 infection compared with RH, where numbers were comparable to naive controls." (PMID 27721814, 2016). "By day 8 post-infection, cells responding to both viruses had similar levels of CD44 and KLRG-1 while maintaining disparate expression of CD25 and PD-1." (PMID 26915099, 2016). "Six days post-infection, lungs and MLN were harvested and CD8+ T cells were analyzed for expression of CD127, CD62L, and KLRG1 and categorized into 4 categories CD127hi, CD62Lhi, KLRG1 lo; CD127hi, CD62Llo; KLRG-1 lo." (PMID 26752171, 2016). "Expression of CD127, CD62L, and KLRG1 was comparable between WT and DKO OT1 cells on day 7 at the peak of infection; however, after day 14 of infection, CD127 expression was lower and KLRG1 expression was higher in DKO OT1 T cells than in WT OT1 T cells." (PMID 27014906, 2016). "As early as day 4 post infection, donor cells responding to Clone 13 not only rapidly proliferated but also up-regulated markers of activation including CD44, KLRG-1, CD25 and PD1." (PMID 26915099, 2016). "KLRG1 expression on cNK cells was induced by all infections with KLRG1 expressed on both mature and immature cNK cells after RH and ME49 infections." (PMID 27721814, 2016). "Our results are indicative of the fact that heterogeneity in the expression of KLRG1 and CD127 following MCMV infection may be associated with the generation of two distinct populations of short-lived effector and long-lived memory cells during progression of infection." (PMID 26720146, 2015). "Strikingly, MCMV infection induced KLRG-1 expression in half of all CD8+ T cells, while infection plus Treg depletion further enhanced the maturation indicated by an increase of up to 80% of KLRG-1+ cells among CD8+ T cells." (PMID 25108672, 2014). "Very few effector CD4+ T-bet+ T cells expressed KLRG-1 in either WT or WSX-1−/− mice on days 0, 7 and 9 of infection." (PMID 23593003, 2013). "Additionally, the presence of mature, HBV-specific memory NK cells (mNKs) was demonstrated in humans exposed to HBV antigens through vaccination or infection, which was mediated by CD56dim NK cells co-expressing CD57, CD69 and KLRG1." (PMID 38793619, 2024).
infection (continued). "The lack of NFAT signaling in OTI cells resulted in reduced KLRG1+CD27- OTI frequency following acute infection." (PMID 38346075, 2024). "Increased KLRG1+CD4+ T-cells may negatively impact immunity by enhancing stromal adherence and restricting the access of terminal effector cells to the infection site." (PMID 38898461, 2024). "(D) Representative flow plots of KLRG1 and CD127 expression on P14 cells at day 31 post infection." (PMID 38127070, 2023). "At day 10 (effector) and day 30 (memory) post-infection, scRNA-seq and scATAC-seq were performed on KO and WT OT-I cells isolated from recipient spleens and labeled with Total-seq antibodies to CD44, CD62L, CD127, and KLRG1." (PMID 37414528, 2023). "Also consistent with reduced Bcl2 expression, increased proportions of dead Malat1scr/scr cells were observed in both the KLRG1+ and KLRG1− cell fractions at day 7 during LM-GP33 infection." (PMID 38127070, 2023). "Notably, CC006 mice that received B6-m157 immunization had more total Ly49H NK cells and KLRG1+CD62L−Ly49H NK cells compared with both naive and B6 immunized hosts, indicating an enhanced recall response following infection." (PMID 35031582, 2022). "The dKO OT-I cells showed higher frequencies of KLRG1+ SLEC in blood of the recipients on day 5 post infection irrespective of their ability to produce autocrine IL-2." (PMID 35477960, 2022). "KLRG1+CD127- CD8+ T population represents short-lived and terminally differentiated effector cells (SLECs), which show robust cytolytic function in controlling infection and undergo rapid contraction after the resolution of infection." (PMID 34618873, 2021). "The CD8+ T cell subsets associated with MCMV-E7 infection were characterized with a higher level of KLRG1, CD39, CD11c, and NKG2A expression compared with single-cycle MCMV-FKBP-E7 infection, reflecting a higher activation status due to persistent antigenic triggering." (PMID 33458613, 2021). "A large pool of TRM cells was induced, as the majority of the OT-I T cells in the lungs expressed the typical TRM markers CD69 and CD103 four weeks post infection, but no sizeable KLRG1+ population was detected." (PMID 33479479, 2021). "Secondary TnikΔ/Δ but not TnikΔ/Δ20 effectors showed lower fraction of Klrg1+Tcf1+ gp33-specific CD8+ T cells compared with TnikWT 4 days after rVV-G2 infection." (PMID 32242021, 2020). "The Bimhi and Bimlo populations on day 10 post-infection had similar frequencies of effector populations defined by KLRG1 and CD127, and both lacked expression of CD62L." (PMID 31558776, 2020). "polygyrus L3 larvae, and at day seven post-infection peritoneal lavage (PL) and lung cells were stained for flow cytometry of ST2 on peritoneal lavage KLRG1+CD25+lineage–CD45+ ILC2s (A, B), lung ICOS+lineage–CD45+ ILC2s (C, D), or peritoneal lavage SSChilineage–CD45+ cells (E, F)." (PMID 32420871, 2020). "Our data show that, regardless of virus strain, the absence of Nrp1 on CD8 T cells at the time of infection resulted in a bias toward KLRG-1− CD127+ memory precursor phenotype cells at the expense of KLRG-1+ CD127− effector cells at the peak of the response." (PMID 31118303, 2019). "Moreover, using new computational tools, it was recently shown that inflationary MCMV-specific T cells are progressively differentiating in time (based on the markers KLRG1, CD44, CD27 and CD62L), long after the initial infection." (PMID 30989333, 2019). "Interestingly, the frequency of PD-1, Tim-3, and KLRG1 positive CD8+ T cells gradually increases and reaches a similar level as during high dose infection after eleven weeks of infection." (PMID 31145756, 2019). "Interestingly, we found that CD8+ T cells in female mice preferentially exhibit a SLEC (KLRG1+CD127−) phenotype, even at early stages of infection (5 dpi), when the overallcellnumbers are similar." (PMID 31317126, 2019).
infection (continued). "Both sequential and simultaneous infection with these viruses resulted in significant and permanent expansion of CD4 and CD8 TEM, to levels consistent with those seen in humans, as well as an increase in KLRG1 expression." (PMID 29963060, 2018). "The same result was obtained at later time points post infection in the spleen with increased CD11a+CD49d+ CD4 T cells expressing KLRG1 in CD11ccre+, but not LysMcre+ mice compared to Cre- controls at day 21 and day 40 p.i." (PMID 30044874, 2018). "Splenic CD4+ T cell and CD8+ T cell activation was, however, largely unaltered, as determined by comparing the levels of granzyme B, KLRG-1, and Ki-67 expression in IFN-γR−/− mice to the levels in VAV-Cre+ IFN-γR2flox/flox mice and WT mice on day 7 of infection." (PMID 28874445, 2017). "Interestingly, expression of CD127, CD62L, CD27, and KLRG1 among Ag-experienced CD8 T cells was different in individual outbred mice, and these differences were magnified as time passed after infection." (PMID 29213267, 2017). "KLRG1 was highly expressed by immature CD11b− subsets and, in particular, within R1 compartment in PEC after RH infection and within R0 and R1 in spleen after ME49 infection." (PMID 27721814, 2016). "Differentiated CD8+KLRG1+ T cells peaked on day 7 and were not yet detectable on day 3 post infection (middle)." (PMID 27875529, 2016). "Thus PBMC from mice infected with 102 or 106 pfu Smith strain were evaluated 42 weeks after infection for expression of CD44, CD27, CD62L, and KLRG1 on tetramer positive mCMV-specific CD8 T-cells." (PMID 27870919, 2016). "The lower level KLRG1 expression seen on virus specific T-cells after low titer infections was not significantly increased by reinfection with high titer K181 (data not shown)." (PMID 27870919, 2016). "After 1° infection with intracellular pathogens such as LCMV, subsets of differentiating 1° effector CD8 T cells can be distinguished based on the expression of phenotypic markers like KLRG1 and CD127." (PMID 26431533, 2015). "In contrast, in WSX-1−/− mice the frequencies, and correspondingly the total numbers, of effector CD4+ T-bet+ T cells expressing KLRG-1 rapidly increased between day 9 and day 11 of infection, such that more than 50% of all splenic effector CD4+ T-bet+ cells expressed KLRG-1 on day 14 of infection." (PMID 23593003, 2013). "However, it has been suggested that a subset of CD27+ KLRG1+ NK cells expand following BCG inoculation and confer protection against M. tuberculosis infection by reducing the CFU numbers in the lungs at 30 days post-infection." (PMID 37486946, 2023). "On days nine and twelve post-infection, the majority of donor P14 let-7Tg CD8 T cells displayed a phenotype of memory precursor effector cells (MPECs: KLRG1-CD127+), while a high proportion of P14 lin28Tg lymphocytes were short lived effector cells (SLECs: KLRG1+CD127−)." (PMID 37696797, 2023). "Likewise, even during acute toxoplasmosis, the co-expression of cell surface receptors KLRG1 and CXCR3 distinguishes CD8+ T cell subsets that have memory potential or are terminally differentiated, with continued presence of infection driving the KLRG1+CXCR3- terminally differentiated population." (PMID 35727849, 2022). "Furthermore, Trm cells, at barrier sites based on their expression of CD69 and CD103, as well as the absence of KLRG-1 and Eomes, are found early during infection at the site of inflammation during an ongoing inflammatory response." (PMID 34608235, 2022). "In contrast, by d140 after infection, we could not observe any differences in splenic Nr2f6-deficient OT-I CD127+KLRG1−, Tcm, or Tem populations." (PMID 33589606, 2021). "Published data shows that a cell-extrinsic increase in KLRG1 is unlikely to be secondary to reduced IL-10 production in Il27ra-/- mice, as Il10-/- and Il10r-/- mice show no (or a very marginal) upregulation of KLRG1 upon infection." (PMID 30044874, 2018).